GTF3C5 (general transcription factor IIIC subunit 5)
Description:
Involved in RNA polymerase III-mediated transcription. Integral, tightly associated component of the DNA-binding TFIIIC2 subcomplex that directly binds tRNA and virus-associated RNA promoters.
Synonyms: TFIIIC63; TFiiiC2-63; TFIIICepsilon
Tractability: PROTAC: ubiquitination databases record sites on it; its protein half-life has been measured.
Gene: Protein-coding gene on chromosome 9 (133,030,675 to 133,058,503, forward strand). Ensembl gene ENSG00000148308.
Subcellular location: Nucleus
Subcellular location (Human Protein Atlas): Nucleoplasm
Pathways (Reactome):
Gene expression (Transcription): RNA Polymerase III Abortive And Retractive Initiation; RNA Polymerase III Transcription Initiation From Type 1 Promoter; RNA Polymerase III Transcription Initiation From Type 2 Promoter
Gene Ontology:
Molecular function: protein binding; RNA polymerase III general transcription initiation factor activity; DNA binding
Biological process: transcription initiation at RNA polymerase III promoter; 5S class rRNA transcription by RNA polymerase III; transcription by RNA polymerase III; tRNA transcription by RNA polymerase III
Cellular component: nucleoplasm; nucleus; transcription factor TFIIIC complex
Genetic constraint (gnomAD): Loss-of-function variants: 42 observed, 51.62 expected, observed/expected ratio (o/e) 0.81, 90% interval 0.63 to 1.05. The upper end of that interval is the gene's LOEUF score, 1.05, which puts it in group 4 of 6, group 1 being the genes least tolerant of losing a copy. Missense variants: 600 observed, 641.8 expected, observed/expected ratio (o/e) 0.93, 90% interval 0.87 to 1. Synonymous variants: 273 observed, 261.64 expected, observed/expected ratio (o/e) 1.04, 90% interval 0.94 to 1.15.
Homologues: Orthologues: chimpanzee GTF3C5 (99% identical), macaque GTF3C5 (99% identical), mouse Gtf3c5 (85% identical), rat Gtf3c5 (83% identical), guinea pig GTF3C5 (83% identical), dog GTF3C5 (82% identical), rabbit GTF3C5 (77% identical), tropical clawed frog gtf3c5 (67% identical), zebrafish gtf3c5 (53% identical), Drosophila melanogaster l(2)37Cd (26% identical), Caenorhabditis elegans tftc-5 (23% identical).
Diseases named in the same sentence as GTF3C5 in open-access papers:
GTF3C5 is named in the same sentence as 4 diseases in open-access papers, as found by Europe PMC text mining. Sharing a sentence is not in itself a finding about the gene and the disease. The quoted sentences say what the papers report.
angina pectoris (1 paper, 2022). The symptom of paroxysmal pain consequent to MYOCARDIAL ISCHEMIA usually of distinctive character, location and radiation. "Also, another rare (MAF=0.001) deleterious rs369889499 (p.Tyr347Cys) variant in GTF3C5 was 77-fold enriched in the Finns- and associated with multiple phenotypes, including angina pectoris (p=9.20×10−5) and ischemic heart disease (p=6.10×10−4)." (PMID 36419110, 2022).
bacteremia (1 paper, 2026). "Variants at GTF3C5 (rs2905094) and DUP4 confer protection against severe malaria and bacteremia." (PMID 41946712, 2026).
GTF3C5 also shares sentences with these, for which no sentence is quoted: ischemic heart disease (1 paper); malaria (1).